ZNF723 (zinc finger protein 723)
Description:
May be involved in transcriptional regulation.
Synonyms: ZNF723P
Tractability: PROTAC: ubiquitination databases record sites on it.
Gene: Protein-coding gene on chromosome 19 (22,832,291 to 22,858,667, forward strand). Ensembl gene ENSG00000268696.
Subcellular location: Nucleus
Gene Ontology:
Molecular function: DNA-binding transcription factor activity, RNA polymerase II-specific; RNA polymerase II cis-regulatory region sequence-specific DNA binding
Biological process: regulation of DNA-templated transcription; regulation of transcription by RNA polymerase II
Cellular component: nucleus
Genetic constraint (gnomAD): Missense variants: 115 observed, 128.72 expected, observed/expected ratio (o/e) 0.89, 90% interval 0.77 to 1.04. Synonymous variants: 52 observed, 43.73 expected, observed/expected ratio (o/e) 1.19, 90% interval 0.95 to 1.5.
Homologues: Paralogues in human: ZNF92 (76% identical), ZNF680 (74% identical), ZNF737 (73% identical), ZNF66 (72% identical), ZNF626 (71% identical), ZNF675 (71% identical), ZNF98 (71% identical), ZNF430 (70% identical), ZNF273 (70% identical), ZNF257 (70% identical), ZNF730 (69% identical), ZNF431 (69% identical), and 6 more.
Diseases named in the same sentence as ZNF723 in open-access papers:
ZNF723 is named in the same sentence as 1 disease in open-access papers, as found by Europe PMC text mining. Sharing a sentence is not in itself a finding about the gene and the disease. The quoted sentences say what the papers report.
cancer (1 paper, 2021). A tumor composed of atypical neoplastic, often pleomorphic cells that invade other tissues. "Notably, the upregulation of TMEM178B and ZNF723 has not been directly linked to carboplatin resistance, and understanding of their biological function in cancer remains limited." (PMID 34440225, 2021).